ZBTB16 (zinc finger and BTB domain containing 16)
Diseases named in the same sentence as ZBTB16 in open-access papers (continued):
Sharing a sentence is not in itself a finding about the gene and the disease.
breast carcinoma (continued). "The role and regulation of ZBTB16 in breast cancer remain to be established." (PMID 32517789, 2020). "Furthermore, in Transwell assays, including a Matrigel barrier, the number of breast cancer cells with ZBTB16 overexpression invading the barrier was markedly decreased relative to control cells." (PMID 32517789, 2020). "Our findings also support the possibility of ZBTB16 being a prognostic biomarker for breast cancer." (PMID 32517789, 2020). "The collective findings of this study suggested that ZBTB16 may be effectively used as a biomarker to improve prognosis and treatment of breast cancer patients." (PMID 32517789, 2020). "In this study, we determined that pyrotinib combined with chrysin could elicit a synergistic superiority in inhibiting HER2-positive breast cancer in vitro and in vitro than single pyrotinib or chrysin treatment via the regulation of miR-16-5p/ZBTB16/G6PD axis." (PMID 38110365, 2023). "Secondly, ZBTB16 may become a prognostic marker for breast cancer and hepatocellular carcinoma." (PMID 34660783, 2021). "However, the specific role of ZBTB16 in breast cancer remains to be established." (PMID 32517789, 2020). "Emerging literature supports that restoration of ZBTB16 led to induction of G2/M phase arrest and reversal of EMT through antagonizing BCL6/ZBTB27 breast cancer." (PMID 38789960, 2024). "Zbtb16 expression is activated by the glucocorticoid receptor (NR3C1) in many cell types, including hepatocytes, breast cancer cell line, endometrial stromal cells, and myometrial smooth muscle cells." (PMID 36768453, 2023). "The intersection of the two datasets manifested 2 potential targets for HER2-positive breast cancer, zinc finger and BTB/POZ domain-containing family protein 16 (ZBTB16) and promyelocytic leukemia protein (PML), which are known as essential tumor suppressors." (PMID 38110365, 2023). "Based on these findings, we proposed that ZBTB16 inhibits migration, invasion, and reverses EMT in breast cancer cells." (PMID 32517789, 2020). "Expression of ZBTB16 and ZBTB28 in most breast cancer cell lines was low or silenced but BCL6 was high." (PMID 32517789, 2020). "This indicates that a high number of infiltrating ZBTB16-expressing cells, such as NKT cells and γδ T cells, constitute a survival benefit for patients with breast cancer." (PMID 29518903, 2018). "Several circRNAs identified in our analysis, including hsa_circRNA_104310 (ZDHHC4, AUC = 0.80), hsa_circRNA_404935 (ZBTB16, AUC = 0.882), hsa_circRNA_003641 (ATM, AUC = 0.876), and hsa_circRNA_102445 (CARM1, AUC = 0.812), demonstrated strong discriminatory power across breast cancer subtypes." (PMID 41516402, 2026). "Certain circRNAs identified in our analysis demonstrated exceptionally strong discriminatory power across breast cancer subtypes, e.g., hsa_circRNA_104310 (host gene: ZDHHC4), hsa_circRNA_404935 (ZBTB16), hsa_circRNA_003641 (ATM), and hsa_circRNA_102445 (CARM1)." (PMID 41516402, 2026). "ZBTB16 functions as a tumor suppressor through upregulating ZBTB28 and antagonizing BCL6, leading to inhibition of migration and invasion, reversal of EMT, and suppression of cell proliferation in breast cancer." (PMID 38789960, 2024). "Afterward, we examined the mRNA expression levels of ZBTB16 and PML in breast cancer tissues." (PMID 38110365, 2023). "The collective results demonstrated that ZBTB16 exerts significant tumor suppressor effects through upregulation of ZBTB28 and downregulation of BCL6 and supported its identity as a prognostic biomarker to improve treatment outcomes of breast cancer." (PMID 32517789, 2020).
breast carcinoma (continued). "Our data also demonstrated ZBTB16 methylation was significantly increased while the expression of ZBTB16 was sharply decreased in 10 breast cancer tissues compared with paired non-cancerous breast tissues." (PMID 32517789, 2020). "RT-PCR analysis showed ZBTB16 expressed in human mammary epithelial cell HMEC and MCF10A, as well as normal adult breast tissues and other human normal tissues (sFig1A), but downregulated or silenced in nine breast cancer cell lines." (PMID 32517789, 2020). "Data from the luciferase assay showed that ZBTB16 suppressed the promoter activity of BCL6 and enhanced that of ZBTB28, indicating that ZBTB16 might play an anti-tumor role in breast cancer through regulating ZBTB28 and BCL6." (PMID 32517789, 2020). "Furthermore, in triple-negative breast cancer (TNBC) and basal-like breast cancer (n = 243) cases, ZBTB16 expression was lower than that in non-basal-like breast cancer and non-TNBC groups (n = 3539) in bc-GenExMiner." (PMID 32517789, 2020). "Consistent with a tumor cell non-autonomous role, injection of wildtype mammary tumor cells into wildtype or Zbtb16+/- animals showed a significant increase in pulmonary colonization in the heterozygous animals without significant effect on primary tumor burden (p = 0.81)." (PMID 27074153, 2016).
melanoma (17 papers, 2009 to 2022). A malignant, usually aggressive tumor composed of atypical, neoplastic melanocytes. "Loss of ZBTB16 expression has been reported in a number of different tumor types including prostate cancer, non-small cell lung cancer, melanoma." (PMID 28122328, 2017).
prostate carcinoma (15 papers, 2013 to 2024). A carcinoma that arises from epithelial cells of the prostate gland. "ZBTB16 knock-down experiments demonstrated increased PCa growth and ectopic expression inhibited prostate cancer tumorigenesis in mouse models." (PMID 33975627, 2021). "ZBTB16 is a classic androgen receptor (AR) regulatory gene, which has antiproliferative activity in prostate cancer cells and plays a role in inhibiting cancer by inhibiting the MAPK pathway." (PMID 34660783, 2021). "Further, loss of ZBTB16 promotes a metastatic and ENZA-resistant phenotype in prostate cancer cells." (PMID 33975627, 2021). "ZBTB16 (also known as PLZF) has been marked as an androgen-responsive gene with anti-proliferative activity in prostate cancer cells." (PMID 30566500, 2018).
metabolic syndrome (13 papers, 2009 to 2025). A cluster of metabolic risk factors for CARDIOVASCULAR DISEASES and TYPE 2 DIABETES MELLITUS. "ZBTB16 is involved in almost all processes underlying the pathogenesis of metabolic syndrome, mainly related to immune function, inflammation, and oxidative stress." (PMID 36661515, 2023). "We used the spontaneously hypertensive rat (SHR) strain and a minimal congenic rat strain SHR-Zbtb16, carrying the Zbtb16 gene allele originating from the PD/Cub rat, a metabolic syndrome model." (PMID 33061941, 2020). "Zbtb16 is a pleiotropic transcription factor involved, among others, in processes underlying pathogenesis of practically all major constituents of metabolic syndrome, as reviewed recently." (PMID 29731739, 2018). "ZBTB16, a transcription factor and epigenetic regulator involved in protein–protein interactions, cell proliferation, and differentiation, has been associated with oxidative stress, metabolic syndrome, and fibrosis." (PMID 38329499, 2024). "On the other hand, the lack of association of the other SNPs (TMEM18 rs6548238 C allele, GPX5 rs445870 G allele, ZPR1 rs964184 G allele, and ZBTB16 rs7106340 T allele) with metabolic diseases (obesity or metabolic syndrome) in this work could have been influenced by the sample size." (PMID 37761915, 2023). "The genomic background of SHR was thought to exacerbate the effects of Zbtb16 gene involved in pathogenesis of metabolic syndrome, but conversely was shown to improve the related parameters, which was to an extent apparent in our study as well." (PMID 32245222, 2020). "We and others previously established the importance of Zbtb16 gene in metabolic syndrome and its nutrigenetic aspects." (PMID 32245222, 2020). "We have recently reviewed in detail the pleiotropic connections of Zbtb16 to the facets of metabolic syndrome, including IR and dyslipidemia." (PMID 29731739, 2018). "The present study aimed to identify associations linking allelic variants of the PCSK1, TMEM18, GPX5, ZPR1, ZBTB16, and PPARG1 genes with anthropometric and biochemical traits and metabolic diseases (obesity or metabolic syndrome) in an adult population from northwestern Mexico." (PMID 37761915, 2023). "In a study of 1517 non-diabetic subjects without hypolipidemic treatment, several single nucleotide polymorphisms in ZBTB16 gene were associated with adiposity measures, LDL, and total cholesterol, suggesting the importance of ZBTB16 for metabolic syndrome in humans." (PMID 29731739, 2018). "In this study, we created two new models, one of them carrying only the Zbtb16 gene from the original segment to retest its effect on DEX-induced metabolic syndrome features by comparing their metabolic profiles including global and tissue-specific insulin sensitivity." (PMID 29731739, 2018). "Intriguingly, AAV-Hep-Glrx treatment also significantly downregulated transcription of the gene Zbtb16 (zinc finger and BTB domain-containing 16), which encodes the transcription factor PLZF (promyelocytic leukemia zinc finger) that controls lymphocyte differentiation and metabolic syndrome." (PMID 35624731, 2022). "ZBTB16, also known as promyelocytic leukemia zinc finger (PLZF), is a transcription factor (TF) that is be related to cardiac hypertrophy and/or fibrosis associated with hypertension and connected to components of metabolic syndrome such as dyslipidemia and insulin resistance via TNFA and IL697." (PMID 33820928, 2021). "One of the genes potentially interconnecting all major components of the metabolic syndrome is zinc finger and BTB domain containing 16 (ZBTB16) transcription factor." (PMID 33061941, 2020). "The metabolic disturbances including impaired glucose tolerance, dyslipidemia, and IR of skeletal muscle observed after DEX treatment in the congenic SHR-Lx.PD5PD-Zbtb16 reveal the Zbtb16 locus as a possible sensitizing factor for side effects of GC therapy." (PMID 29731739, 2018).
acute myeloid leukemia (12 papers, 2011 to 2025). Acute myeloid leukemia (AML) is a group of neoplasms arising from precursor cells committed to the myeloid cell-line differentiation. "This is the first report showing the mutational landscape of the rare ZBTB16‐RARA rearranged acute myeloid leukemia (AML)." (PMID 34042280, 2021). "ZBTB16, Also known as myeloid leukemia zinc finger protein (PLZF), it was first discovered in 1993 in the study of acute myeloid leukemia, and as a transcription inhibitory factor, it may affect the tumor immune microenvironment by regulating the NF - κ B pathway." (PMID 40552012, 2025).
cardiac hypertrophy (9 papers, 2012 to 2021). "ZBTB16, a Kruppel-like zinc finger protein, highly expressed in the heart, is an important TF that regulates cardiac hypertrophy through the Ang II receptor 2 in response to angiotensin II." (PMID 32595699, 2020). "Furthermore, Zbtb16 is known to regulate GATA4 transcription and has a proposed role in cardiac hypertrophy." (PMID 30410445, 2018).
Obesity (9 papers, 2013 to 2025). Accumulation of substantial excess body fat. "ZBTB16 is expressed in various tissues and plays a variety of biological functions through the regulation of tissue-specific target genes, which is related to adipogenesis, myocardial remodeling, osteoblast differentiation, and obesity." (PMID 34660783, 2021). "In the obesity signature, eight genes were found to possess regulatory functions: COPS5, GATA2, MORF4L1, OPTN, PFDN5, SETBP1, TCF4, and ZBTB16." (PMID 40102990, 2025). "Morbid obesity, regardless of the degree of insulin resistance, was associated with changes in the expression of genes involved in pro- (such as CD86 and S100A8) and anti-inflammatory (such as CCL18 and ZBTB16) responses." (PMID 35625760, 2022).
lung carcinoma (8 papers, 2020 to 2025). "Our research found that the expression of ZBTB16 is significantly reduced in lung cancer, which is associated with disease progression." (PMID 40552012, 2025). "Firstly, this study aims to evaluate the diagnostic significance of ZBTB16 in lung cancer and other cancers, but only analyzed its ROC in lung cancer and did not extend to other cancers." (PMID 40552012, 2025). "ROC curve analysis showed that ZBTB16 is associated with lung cancer prognosis, with an AUC of 0.93, specificity and sensitivity of 95.37% and 79.06%, respectively." (PMID 40552012, 2025). "Through immunohistochemistry (IHC) staining, measurement of ZBTB16 expression levels in the TCGA database, and quantitative polymerase chain reaction (qPCR) confirmation, it was found that ZBTB16 is downregulated in lung cancer samples, indicating its potential role as a diagnostic biomarker." (PMID 40552012, 2025). "We also conducted univariate and multivariate Cox regression analysis using the TCGA database to explore the correlation between ZBTB16 and lung cancer, including pathological T stage, N stage, age, and pathological stage." (PMID 40552012, 2025). "The results showed that the expression of ZBTB16 decreased with the progression of lung cancer and was statistically significant (P < 0.05)." (PMID 40552012, 2025). "The aim of this study is to use bioinformatics to analyze the potential of ZBTB16 as an immune biomarker in lung cancer and various other cancers." (PMID 40552012, 2025). "ZBTB16 is at the core of this module, indicating its important role in the occurrence and development of lung cancer." (PMID 40552012, 2025). "Further in vivo studies are essential to validate the role of ZBTB16 in the development of lung cancer and other types of cancer, and understanding its molecular mechanisms is critical for the development of targeted therapies." (PMID 40552012, 2025). "In summary, our study revealed for the first time that ZBTB16 is a potential tumor suppressor gene in lung cancer and many other cancers, affecting cell migration, invasion, proliferation, and apoptosis." (PMID 40552012, 2025). "Then, the potential role of ZBTB16 in the occurrence and progression of lung cancer was verified, and immune invasion analysis, pan-cancer analysis and mRNA-miRNA link analysis were performed." (PMID 40552012, 2025). "Secondly, the validation of ZBTB16 expression in lung cancer was conducted solely through quantitative Polymerase Chain Reaction (qPCR), omitting other techniques such as Western blotting (WB) or Immunohistochemistry (IHC) for a more comprehensive validation." (PMID 40552012, 2025). "This in-depth exploration reveals the expression of ZBTB16 in lung cancer, paving the way for understanding the molecular mechanisms of lung cancer." (PMID 40552012, 2025). "Analysis using R software (4.2.1) showed significant differences in ZBTB16 expression levels between lung cancer tissue and normal tissue." (PMID 40552012, 2025). "Overall, we found a significant reduction in ZBTB16 levels in lung cancer, providing key insights for an accurate diagnosis." (PMID 40552012, 2025). "The KM plot analysis showed that the overregulation of three oncogenes (SOX4, BZW2, and FOXM1) as well the downregulation of four tumor suppressors (SOX17, ZBTB16, TAL1, and KLF4) is associated with worse overall survival (OS) for lung cancer patients." (PMID 36661515, 2023). "The downregulation of ZBTB16 in the cytoplasm of NSCLC lung cancer cells has been related to high tumor grade and tumor aggression." (PMID 36101460, 2022). "Overexpression of ZBTB16 in lung cancer cell lines inhibited proliferation and increased apoptosis while the depletion of cytoplasmic PLZF was correlated with the high tumor grade, lymph node metastasis, the higher tumor stage and the shorter overall survival." (PMID 32998690, 2020).
lung carcinoma (continued). "In addition, the expression heterogeneity of ZBTB16 will be analyzed based on TCGA lung cancer subtype data to develop subtype specific treatment strategies." (PMID 40552012, 2025). "Relationship between ZBTB16 expression and clinicopathological features in lung cancer patients." (PMID 40552012, 2025). "In lung cancer, low expression of ZBTB16 may lead to excessive activation of NF - κ B signaling, promoting the infiltration of immune suppressive cells (such as regulatory T cells) and forming a pro tumor microenvironment." (PMID 40552012, 2025). "WGCNA analysis shows that ZBTB16 is significant in lung cancer." (PMID 40552012, 2025). "Then, TCGA database, Human Protein Atlas database, and whole blood qPCR testing were used to verify the differential expression of ZBTB16 in lung cancer, and immune invasion analysis of ZBTB16 in lung cancer, pan cancer analysis of ZBTB16, and mRNA miRNA linkage analysis of ZBTB16 were performed." (PMID 40552012, 2025). "Therefore, this article selects ZBTB16 as a DEGs for further research, and verifies its expression in lung cancer through clinical information from the TCGA database and quantitative polymerase chain reaction (qPCR)." (PMID 40552012, 2025). "Three validation methods and pan cancer analysis all showed that the expression of ZBTB16 was reduced in lung cancer and various cancers, which may be a key gene for the occurrence and development of lung cancer and various cancers." (PMID 40552012, 2025). "According to the TRN of lung cancer, SOX4, FOXM1, ETV4, HOXC6, and E2F3 are the main positive regulators, whereas SOX17, KLF4, and ZBTB16 are the main negative regulators of transcription, controlling the expression of other TFs and target genes in lung cancer." (PMID 39228892, 2024). "ZBTB16 is underexpressed in multiple cancer types, including lung cancer." (PMID 36552262, 2022). "We analyzed its expression in lung cancer samples, and immunohistochemistry results from the HPA database showed a decrease in ZBTB16 protein levels in lung cancer tissues, consistent with previous results." (PMID 40552012, 2025). "The seven top deregulated transcription factors (SOX4, SOX17, BZW2, FOXM1, ZBTB16, TAL1, and KLF4) consistently appear to be co-expressed with other frequent DEGs and transcription factors throughout the analysis in lung cancer and PAH." (PMID 36661515, 2023). "Previous studies have shown that ZBTB16 plays an important role in various systemic tumors, but its function in lung cancer has not been revealed." (PMID 40552012, 2025). "Although ZBTB16 has been proved to have tumor suppression function in blood tumors and solid tumors (such as liver cancer and pancreatic cancer), its regulatory network and immune correlation in lung cancer have not been clear." (PMID 40552012, 2025). "In addition, ZBTB16 limits tumor metastasis in other cancers by inhibiting the EMT process, suggesting that it may inhibit invasive phenotypes through a similar mechanism in lung cancer." (PMID 40552012, 2025).